HIF1A (hypoxia inducible factor 1 subunit alpha)
Diseases named in the same sentence as HIF1A in open-access papers (continued):
Sharing a sentence is not in itself a finding about the gene and the disease.
periodontitis (continued). "HIF1A pathway has been found to modulate immunosuppressive molecules, typically VEGF, in periodontitis, and tumor microenvironment." (PMID 33777111, 2021). "Both HIF-1α and TNF were increased in gingival crevicular fluid both in chronic and in aggressive forms of periodontitis." (PMID 32831635, 2020). "However, the relationship between substance P and HIF-1α in rat periodontitis is still unknown." (PMID 32000757, 2020). "Nevertheless, this study investigated the salivary concentrations of HIF-1α in patients diagnosed with periodontitis, irrespective of the degree of disease severity and extent (i.e., the stage and grade of the disease)." (PMID 38744330, 2025). "Conclusion rs1951795 SNP of HIF-1α has no significant impact on the progression of periodontitis and the salivary level HIF-1α." (PMID 38744330, 2025). "rs1951795 A207C SNP at HIF-1α had no role in periodontitis severity and progression as well as on biomarker level associated with this gene." (PMID 38744330, 2025). "NFAT5 mRNA was downregulated in periodontitis tissues (p = 0.037), but HIF-1α was not affected (p = 0.60)." (PMID 36142220, 2022). "The objective of the present study was to explore hypoxia-related miRNA target genes for HIF-1α and NFAT5, as well as miRNA-20a, miRNA-30e, and miRNA-93 expression in periodontitis versus healthy gingival tissues and gingival mesenchymal stem cells (GMSCs) cultured under hypoxic conditions." (PMID 36142220, 2022). "Of the top 10 hub TFs, six “leader” immunosuppressive TF-target DEGs with plausible literature evidence were identified as key to periodontitis pathogenesis and included the down-regulated TFs (NFKB1, FOS, and JUN), as well as up-regulated TFs (HIF1A, STAT5B, and STAT4)." (PMID 33777111, 2021). "Furthermore, our results suggest that NFAT5, but not HIF-1α mRNA, was downregulated in periodontitis patients, suggesting that the activation of miRNAs is potentially associated with NFAT5 expression in periodontal tissues." (PMID 36142220, 2022). "Furthermore, an immunotherapy therapy for OIIRR in periodontitis individuals during OTM, by using HIF-1α along with PD-L1-targeted inhibition, may contribute to the immune response." (PMID 35805974, 2022). "In addition, high HIF-1α and NFATc1 levels were detected in severe periodontitis and gingival crevicular fluid samples of severe periodontitis patients, suggesting a role for the TNF-α/HIF-1α/VEGF pathway in the pathogenesis of periodontitis." (PMID 36142220, 2022). "However, the levels of HIF-1α mRNA were similar in both groups, suggesting that the studied miRNAs (miRNA-20a, miRNA-30e, and miRNA-93) could be involved in the downregulation of NFAT5 in periodontitis tissues." (PMID 36142220, 2022).
brain injury (24 papers, 2014 to 2025). Acute and chronic (see also brain INJURIES, CHRONIC) injuries to the brain, including the cerebral hemispheres, CEREBELLUM, and brain STEM. "SBDP145, sLOX-1, HMGB1, and HIF-1α levels were found to be significantly elevated in preterm newborns with brain injury." (PMID 39256844, 2024). "On this basis, this study will investigate the correlation of SBDP145, melatonin, sLOX-1, HMGB1 and HIF-1α in preterm infants suffering from brain injury." (PMID 39256844, 2024). "Our study aims to assess the significance of SBDP145, melatonin, sLOX-1, HMGB1 and HIF-1α in preterm infants with brain injury." (PMID 39256844, 2024). "The independent variables were SBDP145, melatonin, sLOX-1, HMGB1, HIF-1α, and the dependent variable was the prognosis of neonates with brain injury." (PMID 39256844, 2024). "Following hypoxia-induced brain injury, the transcription complex of hypoxia-inducible factor 1 subunit alpha (HIF-1α) is activated, resulting in the activation of multiple genes that enable cells to adjust to hypoxia and, therefore, recover from cell death." (PMID 36422479, 2022). "Further in line with our findings, pharmacological suppression of HIF1A due to 2-methoxyestradiol is known to induce a decline in the expression of AQP4 following traumatic brain injury." (PMID 35764613, 2022). "Although several previous studies used 2ME2 in the context of TBI and other types of acute brain injuries, they mainly explored the roles of HIF1α in brain edema formation, BBB disruption, and neuroprotection at the early stages of brain injury." (PMID 35177771, 2022). "Pharmacological inhibition of trauma-induced Hif1a activation has previously been shown to enhance necrotic lesion formation after brain trauma, suggesting a neuroprotective role for Hif1a activation in concussive injury." (PMID 34473622, 2021). "In OGD-cultured primary astrocytes, HIF-1α was found to be partly involved in the VEGF-mediated astrocyte response in chronic ischemic brain injury, ultimately leading to the destruction of BBB integrity." (PMID 34966392, 2021). "This is consistent with previous reports that HIF-1α can be strongly regulated by the redox environment, a mechanism that is of particular importance in the setting of ischemic brain injury because of the intrinsic changes in redox status." (PMID 24887017, 2014). "HIF-1α also participates in necroptosis in ischemic brain injuries." (PMID 39570876, 2024). "The results of this study showed that after single and multiple factor logistic regression analysis, SBDP145, melatonin, sLOX-1, HMGB1 and HIF-1α could be used as influential factors in assessing the prognosis of neonates with brain injury." (PMID 39256844, 2024). "Researches support the important role of HIF1A as a neuroprotector in ischemic brain injury." (PMID 36060663, 2022). "Acute high-dose alcohol intake upregulated HIF-1α in a rat model of traumatic brain injury." (PMID 34869620, 2021). "Therefore, the increased expression of EPO regulated by HIF-1α could provide a neuronal protective effect by increasing erythropoiesis to improve oxygen delivery during ischemic brain injury." (PMID 34966392, 2021). "Moreover, it has been reported that HMOX-1 derived metabolites including CO activated the mitochondrial function of astrocytes via HIF-1α/estrogen-related receptor α (ERRα) circuit and therefore play an important role in the repair of neurovascular function after ischemic brain injury." (PMID 32408627, 2020). "iCIRP overexpression in neurons downregulates hypoxia-inducible factor-1α (HIF-1α) expression and HIF-1α-mediated neuronal apoptosis in hypoxic-ischemic brain injury in neonatal rats." (PMID 39838468, 2025). "We found that various in vitro and in vivo models of traumatic brain injury (TBI) markedly enhanced LRRK2 expression in neurons and also increased the level of hypoxia-inducible factor (HIF)-1α." (PMID 30420654, 2018).
brain injury (continued). "Interestingly, a previous study demonstrated that a reduced expression of miR-491-5p activates the MT2-mediated HIF-1α/VEGF/MAPK pathway, thereby promoting angiogenesis in the injury site after traumatic brain injury in mice." (PMID 41009355, 2025). "Exogenously administered NO metabolite S-nitrosoglutathione (GSNO) was found not only to stabilize HIF-1α and to induce HIF-1α-dependent genes but also to stimulate the regeneration process and to aid in functional recovery in traumatic brain injury animal model." (PMID 34439764, 2021). "By knocking out the HIF-1a gene, Helton found that HIF-1a reduced the expression of inflammatory mediators such as COX-2, tumor necrosis factor-alpha (TNF-alpha), and IL family proteins following hypoxic-ischemic brain injury." (PMID 33213432, 2020). "The results of this study showed that the levels of SBDP145, sLOX-1, HMGB1 and HIF-1α in the group of preterm infants with brain injury were higher than that of premature newborns without brain injury, and the level of melatonin was lower than that in the premature infant group (P < 0.05)." (PMID 39256844, 2024). "Furthermore, HIF-1α is suggested to promote neurogenesis in brain ischemic rats and regulate the SDF1-CXCR4 axis to enhance bone marrow-derived mesenchymal stromal cell migration in rats with traumatic brain injury." (PMID 35163700, 2022).
Cognitive impairment (24 papers, 2017 to 2026). Abnormal cognition is characterized by deficits in thinking, reasoning, or remembering. "Our findings indicate that advanced age, lower educational attainment, and elevated HIF-1α levels are correlated with an increased risk of cognitive impairment." (PMID 39717345, 2024). "As a result, age, HIF-1α, and education level were found to be independent risk factors for cognitive impairment." (PMID 39717345, 2024). "In chronic hypobaric hypoxia, neuronal apoptosis induced by HIF-1α in the hippocampus is a significant cause of cognitive impairment." (PMID 36291237, 2022). "HIF-1α is an independent risk factor for cognitive impairment." (PMID 39717345, 2024). "Cognitive impairment in patients undergoing maintenance hemodialysis (MHD) was found to be associated with older age, lower level of education, and higher HIF-1α levels." (PMID 39717345, 2024). "Our findings suggest a positive correlation between HIF-1α levels and the incidence of cognitive impairment." (PMID 39717345, 2024). "Consistent with this, following TBI, increased LRRK2 expression has been observed to be associated with increased hypoxia-inducible factor 1-α (HIF-1α), while inhibition of LRRK2 reduced neurodegeneration, neuroinflammation and cognitive deficits." (PMID 38026695, 2023). "Our data strongly support that chronic hypoxia promotes HIF-1α expression, leading to LCMT1/PP2Ac deficiency and tau hyperphosphorylation, finally resulting in cognitive impairments." (PMID 36555780, 2022). "Conversely, downregulation of HIF-1α attenuates hypoxia-induced tau pathologies and cognitive impairment." (PMID 36555780, 2022). "In the current study, we provide extensive evidence demonstrating chronic hypoxia upregulating HIF-1α, decreasing the level of LCMT1, leading to PP2A deficiency, and resulting in tau hyperphosphorylation and cognitive impairments." (PMID 36555780, 2022). "In our study, increased HIF-1α expression was accompanied with cognitive impairment in ALI mice, suggested a direct connection between the two issues." (PMID 34772431, 2021). "The effect of DMF on the cognitive impairment-related factor HIF-1α level in lung and brain tissues was also examined by Western blot." (PMID 34772431, 2021). "The present study first reported that LA supplementation effectively induced HIF-1α expression and alleviated cognitive deficits in Tau P301S mice (an AD mouse model) by reinstating glucose metabolism impairment via the BDNF/TrkB/HIF-1α signaling pathway." (PMID 32973490, 2020). "The results demonstrated that the downregulation of HIF-1α accumulation during 2VO reduced the compensatory angiogenesis, and aggravated neuronal damage and cognitive impairment induced by 2VO." (PMID 28106731, 2017). "Once we determined that pLVx-GFP-shHIF-1α prevents HIF-1α protein accumulation in the hippocampus and cortex under hypoperfusion, we explored the effects of reducing HIF-1α accumulation on CCH-induced cognitive impairment." (PMID 28106731, 2017). "Collectively, our outcomes propose that RES may counteract cognitive impairments in rats resulting from maternal hypoxia during pregnancy by modulating the hippocampal SIRT1/HIF‐1α pathway." (PMID 40084394, 2025). "Our research indicates that PIH exposure could provoke inflammation and synaptic dysfunction, with RES potentially reversing cognitive deficits by influencing the SIRT1/HIF‐1α pathway." (PMID 40084394, 2025). "This decrease implies that synaptic plasticity disruptions could be the root of cognitive impairments linked to PIH, possibly because of the disruption of the SIRT1/HIF‐1α signaling pathway." (PMID 40084394, 2025). "However, patients undergoing maintenance hemodialysis (MHD) are more likely to experience cognitive impairment, which is related to older age, lower educational attainment and higher HIF-1α levels." (PMID 41189963, 2025).
Cognitive impairment (continued). "Altogether, these findings suggest that elevated hypocretin‐1 levels may induce impaired glycolysis through the regulation of HIF‐1α, culminating in decreased lactate, synaptic damage, and cognitive impairment." (PMID 39119889, 2024). "Excessive hypocretin‐1 conducted with hypocretin receptor 1 (HCRTR1) reduced lactate production and brain‐derived neurotrophic factor (BDNF) expression by hypoxia‐inducible factor‐1α (HIF‐1α), thus impairing adult hippocampal neuroplasticity, and cognitive impairment in CUMS model." (PMID 39119889, 2024). "In addition, administration of echinomycin rescues cognitive deficits, ameliorates HIF-1α and BNIP3L-mediated neuronal pyroptosis and damaged mitochondrial structures, and decreases the expression of TNF-α and IL-6 in the hippocampus." (PMID 36569834, 2022). "Hippocampal HIF-1α contributed to the increase in isoflurane-induced cognitive disorders." (PMID 36291237, 2022). "In addition, the hypoxia has important role to the onset of cognitive impairment via the activation of HIF-1α." (PMID 34772431, 2021). "The correlation between HIF-1α downregulation at 60 dpi and long-term outcome cognitive deficits after CCI may suggest a functional role for HIF-1α in the chronic period." (PMID 31440141, 2019). "Hence, elevated hypocretin‐1 level may regulate the expression of glycolysis‐related factors and lactate release in the hippocampus through negative regulation of HIF‐1α, contributing to impaired neuroplasticity and cognitive impairment in depression." (PMID 39119889, 2024). "Furthermore, in hypoxia-activated astrocytes, hypercapnia induces HIF-1α nuclear translocation, and this may be an available target for improving cognitive impairment." (PMID 36291237, 2022). "Meanwhile, Hif‐1α might enhance O2 supply to Ngb and prevent cognitive impairment." (PMID 34146386, 2021). "Thus, inhibiting HIF-1α may alleviate hypoxia-related cognitive impairment." (PMID 38594359, 2024). "Reduce HIF-1α and Bax expression, increase Bcl-2 expression, initiate the PI3K/Akt pathway, and improve cognitive impairment." (PMID 39399315, 2024). "Increased miR-146a-5p levels in microglia improved NLRP3 inflammasome and inflammatory factors by targeting the regulation of HIF1α/mtROS pathway, and inhibition of NLRP3 inflammasome alleviated cognitive impairment of mice exposed to IH." (PMID 37312196, 2023). "Our further study showed that conversely, HIF-1α silencing recovered chronic hypoxia-induced LCMT1/PP2Ac/tau axis alterations and attenuated cognitive impairment, strongly supporting that HIF-1α downregulates the LCMT1/PP2Ac axis to induce tau pathology." (PMID 36555780, 2022). "Together, our data strongly support the notion that HIF-1α regulates LCMT1 and lowers PP2A activity, mediating tau phosphorylation and cognitive impairments in chronic hypoxia." (PMID 36555780, 2022). "Further, we also found that DMF pretreatment suppressed the HIF-1α level of lung and brain tissues in LPS-triggered ALI mice, as well as the cognitive impairment alleviation." (PMID 34772431, 2021). "Prenatal intermittent hypoxia (PIH) exposure could provoke inflammation and synaptic dysfunction leading to cognitive impairment, resveratrol potentially reversing cognitive deficits by influencing the SIRT1/HIF‐1α pathway." (PMID 40084394, 2025). "Furthermore, the use of HIF-1α inhibitors improved the BBB disruption and can be considered to be potential therapeutic strategies for hypoxia-induced cognitive disorders." (PMID 36902491, 2023). "Given that AF has been shown to alleviate cognitive disorders and MAP2K1 regulates the HIF‐1α signaling pathway, while hyperuricemia activates the ERK pathway influencing HIF‐1α, we investigated whether AF improves HUA‐CI by modulating the HIF‐1 signaling pathway." (PMID 41561638, 2026).
Cognitive impairment (continued). "Hence, our findings imply that HIF-1α downregulating PP2A activity and promoting tau phosphorylation might be a mechanism-based therapeutic target for treating chronic hypoxia-related cognitive deficits including in AD." (PMID 36555780, 2022).
gastric tumor (24 papers, 2009 to 2025). "HIF-1α overexpression was more prevalent in diffuse-type gastric cancers than intestinal-type gastric tumours." (PMID 39816318, 2024). "Overall, HIF-1α is considered a useful independent prognostic factor in GC, and gastric tumour growth, angiogenesis and angiogenesis can be inhibited by suppressing HIF-1α activity." (PMID 38143746, 2023). "It is possible that the same biologic effectors of Akt and HIF1-α are activated in the AGS-EBV gastric tumors through subtle effects of the noncoding RNAs." (PMID 31584998, 2019). "In that study, the analyses of gastric tumors did identify activation of Akt and HIF1-α using immunohistochemistry on tumor samples." (PMID 31584998, 2019). "HIF-1α overexpression in gastric tumor tissues triggers abnormal expression of a gene network to promote the progression of cancer." (PMID 29899167, 2018). "Hypoxia is frequently observed in a spectrum of solid tumors, including gastric tumor, and affects gene expression and cell behavior mainly through HIF1α, a master regulator of hypoxia signaling." (PMID 27329598, 2016). "In fact, the targeted inhibition of HIF-1α has been shown to inhibit the growth of gastric tumors in animals." (PMID 24614305, 2014). "HIF-1α expression was also negatively correlated with CD133 expression in gastric tumor specimens." (PMID 36846589, 2023). "However, upregulation of HIF-1α was observed more commonly in diffuse-type gastric tumors, compared with intestinal-type gastric tumors." (PMID 36846589, 2023). "However, in undifferentiated gastric tumors, CD133 expression was predominant at the cytoplasm and associated with a higher rate of HIF-1α positivity." (PMID 36846589, 2023). "The expression of ACTA2, HIF1A, and VEGFA was independently associated with TJP1 in non-cancerous tissue, explaining 90% in its variability, and BCL2, HIF1A, CDKN1A, and PTGS2 were independently associated with TJP1 in gastric tumors, explaining 98% in gene variability." (PMID 32630408, 2020). "The expression of PTGS2, BCL2, and IL7 (inversely) was independently associated with CCL2 in non-cancerous tissue, explaining 88% in gene variability, and HIF1A and BCL2 were independently associated with CCL2 in gastric tumors, explaining 83% in its variation." (PMID 32630408, 2020). "In addition, immunohistochemical expression of HIF-1α target genes (Glut1, VEGF, CA9, iNOS) is associated with gastric tumor progression." (PMID 22479608, 2012). "HIF-1α has been reported to increase gastric tumor growth and angiogenesis." (PMID 21696576, 2011). "Furthermore, the prognostic role of HIF-1α in gastric tumor had been searched in many trials." (PMID 24614305, 2014). "Hence, tissue-infiltrating gastric tumour cells seemed particularly reliant on HIF-1α." (PMID 19223895, 2009). "In differentiated gastric tumors, CD133 was predominantly expressed at the luminal site of the cancer cells and correlated with a lower rate of HIF-1α positivity." (PMID 36846589, 2023). "We used the PubMed MeSH terms “hypoxia and stomach neoplasms”, “HIF-1α and stomach neoplasms”, “hypoxia and neoplasms”, and “HIF-1α and neoplasms” to search the literature for studies published till 1 January 2022." (PMID 35681691, 2022). "Our results also demonstrated that K5 significantly inhibited the expression of HIF-1α, VEGF, and CD34 in xenograft gastric tumours in mice and in SGC-7901 tumour cells." (PMID 29072683, 2017).